ITK (IL2 inducible T cell kinase)
Diseases named in the same sentence as ITK in open-access papers (continued):
Sharing a sentence is not in itself a finding about the gene and the disease.
Autoimmunity (5 papers, 2020 to 2026). The occurrence of an immune reaction against the organism's own cells or tissues. "Among IEIs, mutations in the interleukin-2-inducible T-cell kinase (ITK) gene are increasingly recognized as a cause of immune dysregulation with a heightened susceptibility to autoimmunity and malignancies." (PMID 39684891, 2024). "Studies of ITK signaling in the pathogenesis of diseases including malignant tumors and autoimmunity are thus an active area of ongoing clinical and preclinical research." (PMID 37266435, 2023). "In context with autoimmunity and inflammatory disorders like IBD, the linkage of TIM-3 and ITK is interesting even though insufficiently investigated." (PMID 41483156, 2026).
chronic GVHD (5 papers, 2015 to 2021). "It is noteworthy that Ibrutinib, an inhibitor of BTK which can also inhibits ITK, is able to reduce chronic GVHD." (PMID 33324410, 2020). "Previous studies have shown that Ibrutinib, an inhibitor of the related Tec kinase Bruton’s tyrosine kinase (BTK) which can also inhibit ITK, is able to reduce chronic GVHD." (PMID 33324410, 2020). "Regarding BTK and ITK pathways, Ibrutinib, a BTK/ITK inhibitor, reduced the severity of chronic GVHD using two established chronic GVHD mice models." (PMID 34526990, 2021). "For the treatment of chronic GVHD, Ibrutinib, an irreversible inhibitor of Bruton's tyrosine kinase (BTK), and Interleukin-2 inducible T-cell kinase (ITK), was recently granted FDA approval and is currently the only one approved for this purpose." (PMID 30211164, 2018).
colitis (5 papers, 2019 to 2023). Inflammation of the colon. "The activation of Interleukin-2-inducible T cell kinase (ITK) was recently shown to be inhibited by cyclosporine A and critically affects the efficacy of calcineurin inhibition in oxazolone-induced colitis." (PMID 37358998, 2023). "However, the same study also revealed that ITK is required for the suppressive function of Tregs in inflammatory diseases: In Rag1−/−, reconstituted with naïve CD4+ cells, a co-transfer of CD4+CD25+ cells, derived from ITKKO mice, could not prevent the development of colitis." (PMID 32808093, 2020).
non-Hodgkin lymphoma (5 papers, 2018 to 2025). Distinct from Hodgkin lymphoma both morphologically and biologically, non-Hodgkin lymphoma (NHL) is characterized by the absence of Reed-Sternberg cells, can occur at any age, and usually presents as a localized or generalized lymphadenopathy associated with fever and weight loss. "Various studies have confirmed the role of ITK in oncogenesis, primarily in Hodgkin and non-Hodgkin lymphoma." (PMID 41301032, 2025). "TCR signaling activates a signaling axis that includes ITK, NF-κB, and GATA-3 and promotes chemotherapy resistance in non-Hodgkin lymphomas." (PMID 36457017, 2022).
psoriasis (5 papers, 2019 to 2025). An autoimmune condition characterized by red, well-delineated plaques with silvery scales that are usually on the extensor surfaces and scalp. "JTE-051 is another ITK inhibitor currently under clinical evaluation for the treatment of rheumatoid arthritis (RA) and psoriasis." (PMID 41567642, 2025). "Moreover, the small molecular bromodomain and extraterminal domain (BET) inhibitors and the inhibitors of interleukin-2-inducible T-cell kinase (ITK) may become effective therapeutics for psoriasis based on different pathways." (PMID 38139164, 2023).
rheumatoid arthritis (5 papers, 2022 to 2025). A chronic, systemic autoimmune disorder characterized by inflammation in the synovial membranes and articular surfaces. "ITK inhibition is a potential treatment for T-cell-mediated inflammatory diseases such as rheumatoid arthritis and can restore the balance between Th17 and regulatory T (Treg) cells." (PMID 40286593, 2025). "Among the modules enriched for genes down-regulated with AD, M123, and its child module M444, anchored by ITK/IKZF3/ETS1, are significantly enriched for MS and rheumatoid arthritis etiologic genes, and, correspondingly, the modules are strongly enriched for a variety of immune functions." (PMID 38343831, 2024).
atopic dermatitis (4 papers, 2014 to 2023). "In patients suffering from atopic dermatitis, elevated levels of ITK were found in peripheral blood T cells." (PMID 32808093, 2020). "ITK mRNA levels in the peripheral blood T cells is elevated in atopic dermatitis patients compared to healthy controls, and this increase correlates with disease severity." (PMID 25250764, 2014). "Furthermore, ITK expression is increased in lesional skin from patients with atopic dermatitis and allergic contact dermatitis." (PMID 25250764, 2014). "However, the molecular mechanism by which ITK drives the inflammatory responses in atopic dermatitis is still unknown and needs to be further elucidated." (PMID 32808093, 2020).
B-cell lymphoma (4 papers, 2017 to 2022). "We measured the phosphorylation of BTK and ITK in B-cell lymphoma or T-cell leukemia cell lines treated with increasing doses of ASK120067 using western blotting." (PMID 36588692, 2022). "Our work demonstrated that ASK120067 exhibited significant anti-tumour activities against B-cell lymphoma and T-cell leukemia in vivo and in vitro, via targeting BTK and ITK." (PMID 36588692, 2022). "Herein, we identified that the third-generation EGFR inhibitor ASK120067 exhibited potency against B-cell lymphoma and T-cell leukemia by targeting BTK and ITK, respectively." (PMID 36588692, 2022). "ITK turned out to be T-cell lineage-specific markers in the setting of lymphoid and myeloid precursor neoplasms but negative in B cell lymphoma." (PMID 30814910, 2019). "Given the success of the BTK inhibitor ibrutinib in the treatment of B cell lymphoma, the TEC family member ITK has become an appealing target for inhibiting TCR signaling, which plays an important role in T cell activation, development, differentiation, and cytokines production." (PMID 30814910, 2019).
Hodgkins lymphoma (4 papers, 2016 to 2025). A heterogeneous group of malignant lymphoid neoplasms of B-cell origin characterized histologically by the presence of Hodgkin and Reed-Sternberg (HRS) cells in the vast majority of cases. "In 2019, a case report of two siblings with biallelic ITK mutation and HPV infection resulted in epidermodysplasia verruciformis, a precancerous lesion that can lead to skin squamous cell carcinoma and Hodgkin lymphoma." (PMID 41301032, 2025).
tuberculosis (4 papers, 2019 to 2023). A chronic, recurrent infection caused by the bacterium Mycobacterium tuberculosis. "Here, we show that the TCR/ITK signaling pathway is enriched in human lungs with active tuberculosis and that Itk deficiency impaired early protection against Mtb in mice, accompanied by defective development of IL-17A-producing γδ T cells in the lungs." (PMID 32038633, 2019). "Inherited ITK deficiency shows incomplete penetrance for severe EBV disease and can underlie severe tuberculosis due to insufficient IFN-γ production by innate-like adaptive (Vδ2+ γδ T and MAIT) and purely adaptive αβ T lymphocytes." (PMID 36326697, 2023). "The same is true for rare inborn errors underlying tuberculosis in humans, including complete IL-12Rβ1 deficiency, certain TYK2 deficiencies, interleukin-2 inducible T cell kinase (ITK) deficiency, and PD1 deficiency." (PMID 37047709, 2023). "Clinical investigation showed that the signal pathway of the T-cell receptor interleukin-2 (IL-2) inducible T-cell kinase (ITK) was altered in patients with active tuberculosis." (PMID 33816327, 2021). "However, the role of ITK signaling pathway in pulmonary responses in active tuberculosis due to Mtb infection is unknown." (PMID 32038633, 2019). "However, the role of the ITK signaling pathway in pulmonary responses in active tuberculosis due to Mtb infection is not known." (PMID 32038633, 2019).
X-linked lymphoproliferative syndrome (4 papers, 2016 to 2025). X-linked lymphoproliferative disease is a hereditary immunodeficiency characterized, in the majority of cases, by an inadequate immune response to infection with the Epstein-Barr virus (EBV). "Nevertheless, the infection had rather mild features, unlike the often catastrophic EBV-driven lymphoproliferative consequences in other inborn errors of immunity, such as in X-linked lymphoproliferative syndrome (XLP) or interleukin-2-inducible T-cell kinase (ITK) deficiency." (PMID 34350147, 2021). "EBV reactivation in primary immunodeficiencies—such as interleukin-2-inducible t-cell kinase (ITK) deficiency, autoimmune lymphoproliferative syndrome (ALPS), and X-linked lymphoproliferative disease (XLP) —remains possible, given their association with EBV-related HLH." (PMID 40863185, 2025).
allergic asthma (3 papers, 2013 to 2019). A asthma with a basis in a pathological type I hypersensitivity reaction. "In view of its role in Th2 cytokine regulation, ITK has been also implicated in the defense against certain parasitic and bacterial infections and in the pathogenesis of lung inflammation such as allergic asthma." (PMID 23667652, 2013). "ITK is thought to drive Th2-mediated disease such as allergic asthma, and ITK-/- mice exhibit significantly improved disease course and reduced bronchoconstriction after antigen re-challenge in ovalbumin sensitized mice." (PMID 31022269, 2019). "The inducible T cell kinase (ITK) regulates type 2 (Th2) cytokines that provide defense against certain parasitic and bacterial infections and are involved in the pathogenesis of lung inflammation such as allergic asthma." (PMID 23667652, 2013).
angioimmunoblastic T-cell lymphoma (3 papers, 2016 to 2020). A mature T-cell non-Hodgkin lymphoma, characterized by systemic disease and a polymorphous infiltrate involving lymph nodes and extranodal sites. "Furthermore, patients who suffer from angioimmunoblastic T cell lymphoma have been found to express significantly more ITK." (PMID 32808093, 2020). "Among mature T-cell neoplasms, subsets of Peripheral T-cell Lymphomas, not otherwise specified (PTCL, NOS) and Angioimmunoblastic T-cell Lymphomas (AITL) display SYK translocations and ITK-SYK fusion proteins." (PMID 26943776, 2016).
metastatic melanoma (3 papers, 2020 to 2025). A melanoma that has spread from its primary site to another anatomic site. "ITK protein expression increased with nevus to metastatic melanoma progression." (PMID 31942187, 2020). "It is not clear whether the lack of consistent improvement in the Th1:Th2 ratio is due to an inadequate exposure of lymphocytes to ibrutinib, or whether the immune milieu of metastatic melanoma patients drives Th2 differentiation in a manner that does not require ITK." (PMID 39967670, 2025).
Obesity (3 papers, 2020 to 2025). Accumulation of substantial excess body fat. "In summary, this study employed bioinformatics analysis of microarray and scRNA-seq datasets to identify three immune hub genes—SPP1, ITK, and CCL5—associated with obesity." (PMID 40725440, 2025). "The identification of SPP1, ITK, and CCL5 as immune hub genes in the adipose tissue of postmenopausal obese women provides new insights into the immune dysregulation associated with obesity." (PMID 40725440, 2025). "But during the progression from obesity to diabetes, galectin-9 could upregulate and trigger phosphorylation of Tyr256 and Tyr263 by the tyrosine kinase ITK, thereby allowing TIM3 to exert the inhibitory function." (PMID 33123595, 2020). "Three genes (ITK, SLFN5, STK10), which have not been linked to diabetes yet, might interact with IFNG and thereby contribute to inflammatory mechanisms usually triggered by obesity." (PMID 32350386, 2020).
pancreatic cancer (3 papers, 2020 to 2025). "The combination of an ITK inhibitor and pembrolizumab was probed in other solid tumors, including mismatch repair proficient metastatic colorectal cancer, metastatic urothelial cancer, and advanced pancreatic cancer." (PMID 39967670, 2025). "In addition, a previously identified ITK inhibitor (NCGC00188382) was shown to inhibit the activity of TAOK3, aurora B kinase, and cyclin-dependent kinase 7 in pancreatic cancer cells and suppress the stemness traits and growth of tumor spheroids." (PMID 33050415, 2020). "In this study, the authors identified an ITK inhibitor, NCGC00188382, which could inhibit the activity of TAOK3, aurora B kinase, and cyclin-dependent kinase 7 in cancer cells and suppress the stemness traits and growth of pancreatic tumors." (PMID 33050415, 2020).
T-cell neoplasms (3 papers, 2016 to 2023). "Moreover we discovered that OTX015 could down-regulate expression of ITK, a kinase known to be overexpressed or deregulated via chimeric fusions in some T-cell neoplasms." (PMID 27793034, 2016). "For example, IL-2 inducible T-cell kinase (ITK), a Tec family kinase and BTK homologue, plays a central role in TCR signaling and is an attractive therapeutic target in T-PLL, and other mature T-cell neoplasms." (PMID 37569479, 2023).
viral infections (3 papers, 2017 to 2020). "Overall, these findings could supply a possible answer to the question why patients with ITK-deficiency have a higher susceptibility to viral infections as well as a decreased viral clearance." (PMID 32808093, 2020). "Moreover, it was demonstrated that patients who have a genetic mutation in the ITK gene locus are more susceptible to virus infection and can thus develop severe diseases affecting the lymphatic system." (PMID 32808093, 2020). "In line with the importance of HS for foamy virus infection, infection of ITK knockdown cells by prototype foamy viruses revealed a 10-fold restriction compared to infection of ITK-expressing Jurkat cells (data not shown)." (PMID 29453458, 2018). "The results showed that wild-type and non-target (n.t.)shRNA Jurkat cells supported HIV-1 replication, whereas ITK knockdown cell lines were resistant to viral infection." (PMID 29453458, 2018). "However, in these latter cases, ITK activation in tumour cells is not linked to a predisposition for viral infections." (PMID 32808093, 2020). "Here we show that ITK, an important modulator of TCR signalling, is required for the TCR-induced development of Tr1 cells in various organs, and in the mucosal system during parasitic and viral infections." (PMID 28635957, 2017). "Here we show that, in the absence of ITK, TCR engagement does not induce optimal differentiation of Tr1 cells in multiple organs and during parasitic or viral infection." (PMID 28635957, 2017).
chronic lymphocytic leukemia (2 papers, 2019 to 2022). "A possible example of this is the treatment of chronic lymphocytic leukemia (CLL) with ibrutinib, a kinase inhibitor that targets BTK on the malignant B cells and ITK on the T cells." (PMID 35844298, 2022).
eosinophilia (2 papers, 2009 to 2013). "The observation that inhibition of ITK activation by R9-QQP causes significant reduction in OVA-inducible eosinophilia further substantiates the critical role that ITK plays in an immune response where Th2 cytokines are involved such as the allergic inflammatory response." (PMID 23667652, 2013). "In both upper and lower airways the allergen exposure led to eosinophilia that was significantly reduced in ITK-/- mice." (PMID 19216740, 2009).
epidermodysplasia verruciformis (2 papers, 2020 to 2025). A rare inherited genodermatosis characterized by chronic infection with human papillomavirus (HPV) leading to polymorphous cutaneous lesions and high risk of developing non melanoma skin cancer. "Recently, another case was presented in two siblings where the mutation of the ITK gene in combination with an infection with the cutaneous human papillomavirus (HPV) type 5 and 8 resulted in epidermodysplasia verruciformis (EV) and Hodgkin lymphoma." (PMID 32808093, 2020).
Graves’ orbitopathy (2 papers, 2022 to 2024). "We investigated the therapeutic effect of ibrutinib, an orally bioavailable BTK/ITK inhibitor, in a mouse model of Graves’ orbitopathy (GO)." (PMID 39280007, 2024).
idiopathic pulmonary fibrosis (2 papers, 2018 to 2022). Idiopathic pulmonary fibrosis (IPF) is a nonneoplastic pulmonary disease that is characterized by the formation of scar tissue within the lungs in the absence of any known cause. "Dysregulated expression of genes, including MMP8, in PBMCs of patients with idiopathic pulmonary fibrosis has been reported, and reduced CD28, ICOS, LCK, and ITK gene expression in PBMCs was associated with poor outcome in cohorts with this disorder." (PMID 29445374, 2018). "Considering the condition that the p-value of survival analysis was less than 0.01 and the p-value of expression difference was less than 0.01, we found that ITK, ZAP70, CD247, and LCK were lower expressed in patients with specific pulmonary fibrosis than in healthy controls." (PMID 35774508, 2022).
influenza (2 papers, 2020 to 2025). An acute viral infection of the respiratory tract, occurring in isolated cases, in epidemics, or in pandemics; it is caused by serologically different strains of viruses (influenzaviruses) designated A, B, and C, has a 3-day incubation period, and usually lasts for 3 to 10 days. "Mice fed a Mg-deficient diet have been reported to exhibit accelerated metastatic spread of cancer cells, and insufficient inducible T-cell kinase (ITK) activity has led to impaired immune responses against influenza in mice due to low Mg intake." (PMID 40948771, 2025).
leukaemia (2 papers, 2020 to 2023). "Ibrutinib, a Bruton's TKI, can remarkably increase peripheral CD4+ and CD8+ T cells in leukaemia patients through the off‐target inhibition of IL‐2‐inducible T cell kinase (ITK) in T cells." (PMID 37403792, 2023). "Our results indicate that ITK signaling is dispensable for anti-leukemia immunity, but required for GVHD." (PMID 33324410, 2020). "Together, these data suggest that the ITK signaling in T cells can separate GVHD from GVL effects, but only for leukemia cells that reside in the circulation and in secondary lymphoid organs (such as hematologic malignancies)." (PMID 33324410, 2020). "We found that these donor cells effectively killed primary leukemia cells in vitro, even in the absence of ITK." (PMID 33324410, 2020).
lung adenocarcinoma (2 papers, 2021 to 2023). A carcinoma that arises from the lung and is characterized by the presence of malignant glandular epithelial cells. "For instance, high ITK expression was found to predict better outcomes of patients with lung adenocarcinomas (LUAD)." (PMID 34282055, 2021). "For instance, high ITK expression is related to better prognosis in lung adenocarcinomas (LUAD)." (PMID 34282055, 2021).
lymphopenia (2 papers, 2017 to 2019). Reduction in the number of lymphocytes. "A murine model of Itk deficiency reveals a similar NKT and T-cell lymphopenia as observed in human patients with ITK deficiency." (PMID 32038633, 2019).
Opportunistic infection (2 papers, 2020 to 2023). An infection that is caused by a pathogen that would generally not be able to cause an infection in a host with a normal immune system. "Patients with deficiencies in ITK and SLP76 presented with recurrent and opportunistic infections, but autoimmune manifestations have been reported in single patients." (PMID 38112969, 2023). "However, Ibrutinib can inhibit T‐cell activation as well by inhibiting ITK 17, which might be responsible for the occurrence of opportunistic infections in treated patients." (PMID 31621069, 2020).